FUT3 (fucosyltransferase 3 (Lewis blood group))
Description:
Catalyzes the transfer of L-fucose, from a guanosine diphosphate-beta-L-fucose, to both the subterminal N-acetyl glucosamine (GlcNAc) of type 1 chain (beta-D-Gal-(1->3)-beta-D-GlcNAc) glycolipids and oligosaccharides via an alpha(1,4) linkage, and the subterminal glucose (Glc) or GlcNAc of type 2 chain (beta-D-Gal-(1->4)-beta-D-GlcNAc) oligosaccharides via an alpha(1,3) linkage, independently of the presence of terminal alpha-L-fucosyl-(1,2) moieties on the terminal galactose of these acceptors. Through its catalytic activity, participates in the synthesis of antigens of the Lewis blood group system, i.e. Lewis a (Le(a)), lewis b (Le(b)), Lewis x/SSEA-1 (Le(x)) and lewis y (Le(y)) antigens. Also catalyzes the transfer of L-fucose to subterminal GlcNAc of sialyl- and disialyl-lactotetraosylceramide to produce sialyl Lewis a (sLe(a)) and disialyl Lewis a via an alpha(1,4) linkage and therefore may regulate cell surface sLe(a) expression and consequently regulates adhesive properties to E-selectin, cell proliferation and migration. Catalyzes the transfer of an L-fucose to 3'-sialyl-N-acetyllactosamine by an alpha(1,3) linkage, which allows the formation of sialyl-Lewis x structure and therefore may regulate the sialyl-Lewis x surface antigen expression and consequently adhesive properties to E-selectin. Prefers type 1 chain over type 2 acceptors. Type 1 tetrasaccharide is a better acceptor than type 1 disaccharide suggesting that a beta anomeric configuration of GlcNAc in the substrate is preferred. Lewis-positive (Le(+)) individuals have an active enzyme while Lewis-negative (Le(-)) individuals have an inactive enzyme.
Synonyms: FucT-III; FT3B; LE; CD174; Les
Tractability: Antibody: UniProt predicts a signal peptide or a membrane-spanning region.
Target class: Enzyme; Transferase
Gene: Protein-coding gene on chromosome 19 (5,842,888 to 5,851,471, reverse strand). Ensembl gene ENSG00000171124.
Subcellular location: Golgi apparatus, Golgi stack membrane
Pathways (Reactome):
Metabolism: Lewis blood group biosynthesis
Metabolism of proteins: Reactions specific to the complex N-glycan synthesis pathway
Gene Ontology:
Molecular function: 3-galactosyl-N-acetylglucosaminide 4-alpha-L-fucosyltransferase activity; 4-galactosyl-N-acetylglucosaminide 3-alpha-L-fucosyltransferase activity; alpha-(1->3)-fucosyltransferase activity; fucosyltransferase activity; protein binding
Biological process: carbohydrate derivative biosynthetic process; cell-cell recognition; ceramide metabolic process; Lewis a epitope biosynthetic process; oligosaccharide biosynthetic process; oligosaccharide metabolic process; positive regulation of cell-cell adhesion; protein N-linked glycosylation; protein O-linked glycosylation; regulation of cell migration; regulation of cell population proliferation; glycoprotein biosynthetic process; sphingolipid metabolic process
Cellular component: extracellular exosome; membrane; Golgi membrane; Golgi cisterna membrane
Genetic constraint (gnomAD): Loss-of-function variants: 3 observed, 1.65 expected, observed/expected ratio (o/e) 1.81, 90% interval 0.62 to 1.94. That is too few expected variants to judge how well the gene tolerates losing a copy. Missense variants: 418 observed, 494.62 expected, observed/expected ratio (o/e) 0.85, 90% interval 0.78 to 0.92. Synonymous variants: 195 observed, 209.59 expected, observed/expected ratio (o/e) 0.93, 90% interval 0.83 to 1.05.
Homologues: Orthologues: chimpanzee FUT3 (93% identical), dog FUT5 (69% identical), tropical clawed frog fut3 (46% identical), tropical clawed frog fut6 (46% identical), tropical clawed frog fut5 (43% identical), zebrafish fut9b.1 (37% identical), zebrafish fut9b.5 (36% identical), zebrafish fut9b.2 (35% identical), zebrafish fut7 (34% identical), zebrafish fut9d (34% identical), zebrafish fut9b.3 (34% identical), zebrafish fut9b.6 (34% identical), and 14 more. Paralogues in human: FUT5 (91% identical), FUT6 (84% identical), FUT4 (42% identical), FUT7 (38% identical), FUT9 (37% identical), POFUT4 (24% identical), POFUT3 (24% identical).
Diseases named in the same sentence as FUT3 in open-access papers:
FUT3 is named in the same sentence as 76 diseases in open-access papers, as found by Europe PMC text mining. Sharing a sentence is not in itself a finding about the gene and the disease. The quoted sentences say what the papers report.
pancreatic cancer (14 papers, 2016 to 2025). "RNA-seq of pancreatic cancer samples revealed that FUT3 expression was higher in the poor prognosis group with elevated CA19-9 levels (q = 0.062)." (PMID 41361823, 2025). "In other types of cancer, FUT3 was involved in the proliferation, migration, tumorigenesis of pancreatic cancer cells." (PMID 34248851, 2021). "Although in vitro and in vivo antibody experiments made the contribution of sLea unlikely, in vivo PM formation from pancreatic cancer was inhibited after decreasing sLex and sLea biosynthesis by blocking fucosyltransferase 3 (FUT3)." (PMID 27074785, 2016). "FUT3 is involved in tumorigenesis, proliferation, and migration of pancreatic cancer." (PMID 36135043, 2022). "The FUT3 gene is also known as the Lewis gene, and the high expression of FUT3 and its product, tetrasaccharide Sialic Lewis x (sLex), has been reported in several types of malignant tumors, such as breast cancer, pancreatic cancer, ovarian carcinoma, and colorectal cancer." (PMID 34948129, 2021). "The high expression of FUT-3 and its product, tetrasaccharide Sialic Lewis x (sLex) has been observed in several kinds of malignant solid tumors, such as oral squamous cell carcinoma, breast invasive ductal carcinoma, pancreatic cancer, ovarian carcinoma and colorectal cancer." (PMID 28977844, 2017). "After the multi-step validation, we identified B3GNT3, B4GALNT3, FUT3, FUT6, GCNT3 and MGAT3 as top-upregulated genes in aggressive pancreatic cancer cell lines Capan-1 and HPAF/CD18." (PMID 32203219, 2020). "Altogether, we have systematically analysed the role of B3GNT3, MGAT3, FUT3 and GCNT3 in pancreatic cancer and illustrated the mechanism of GCNT3 in PC." (PMID 32203219, 2020). "Among these, we successfully identified the functions of B3GNT3, GCNT3, FUT3 and MGAT3 in pancreatic cancer cells." (PMID 32203219, 2020). "Besides, upregulation of FUT3 is a marker of lower overall survival of breast cancer, and knockdown of FUT3 inhibits the proliferation, migration, tumorigenesis, and TGF-β induced EMT in pancreatic cancer." (PMID 38670309, 2024).
breast carcinoma (11 papers, 2011 to 2024). "In other reports, the main α1,3/4‐FUTs associated with sLeX biosynthesis in breast cancer included FUT3, FUT6, and FUT7." (PMID 29215790, 2018). "A total of nine cases with the CNA containing the fucosyltransferase 3 (FUT3) gene at 19p13.3 were observed in the current study, and this gene is associated with breast cancer." (PMID 29083376, 2016). "Firstly, meta-analysis of breast cancer data shows that high levels of expression of FUT1 and FUT3 are associated with a bad prognosis." (PMID 26908442, 2016). "A previous study demonstrated that increased fucosylation of Lewis-x antigens by 5 fucosyl-transferases (FUT-3, -4, -5, -6, and -7) was detected in breast cancer cells that preferentially metastasized to the bone." (PMID 26204487, 2015). "Increased fucosylation of Lewis-x antigens by 5 fucosyl-transferases (FUT-3, -4, -5, -6, and -7) was detected in breast cancer cells that preferentially metastasized to the bone." (PMID 26204487, 2015). "Thus, it seems contradictory that in breast cancer cell lines, induction of EMT leads to repression of FUT3 expression and suppression of both neutral and sialylated Lewis antigens presentation." (PMID 26908442, 2016). "We found that only FUT8, not FUT3, FUT11, POFUT1, or POFUT2, was closely and positively correlated with B7H3 in breast cancer tissues." (PMID 33976130, 2021). "In addition, in silico analyses showed that the mRNA levels of fucosyltransferase genes FUT2, FUT3, and FUT7 also upregulated in breast cancer tissues compared with the adjacent noncancerous breast tissues in 113 pairs of breast cancer from the TCGA database." (PMID 33976130, 2021).
colon carcinoma (7 papers, 2011 to 2024). "Intriguingly, the induction of epithelial-mesenchymal transition (EMT) in colon cancer led to the upregulation of FUT3, ST3GAL3 and ST3GAL4, which are implicated in the final steps of the biosynthesis of sLex/a, suggesting a significant link between those Lewis antigens and EMT in colon carcinoma." (PMID 32872308, 2020). "However, recent studies have linked several mutations in FUT3 to the risk of colon cancer, peptic ulcer, atrophic gastritis, Norovirus infection, type 2 diabetes and coronary heart disease." (PMID 26766790, 2016). "They reported that, when EGF was used in colon cancer cell lines, glycosyltransferase, including FUT3, FUT6, and ST3GAL1/3/4, was elevated." (PMID 38528852, 2024). "AQP1, a Colton blood group antigen system gene, was reported to be associated with poor prognosis in colon cancer and lung adenocarcinoma, while seven of the fifteen genes were reported to be prognostic in one tumor type (GCNT2, FUT7, FUT3, FUT2, DARC, CR1 and BSG)." (PMID 35955933, 2022). "The FUT3 expression upregulates sensitivity of TRAIL pathway in colon cancer patients." (PMID 28977844, 2017). "Previous study indicates that NEU4 desialylates cell surface sLeA/X to LeA/X without affecting the expression of ST3GAL3, ST3GAL4, FUT3, and FUT7 in colon cancer cells." (PMID 34135905, 2021).
colorectal cancer (7 papers, 2017 to 2024). A primary or metastatic malignant neoplasm that affects the colon or rectum. "Similar up-regulation of Fut3 expression has been observed in the serum of patients with liver and colorectal cancer." (PMID 38911244, 2024). "In oncologic researches, FUT3 has been found to be up-regulated in cancerous tissue of human colorectal cancer." (PMID 28977844, 2017). "Low FUT3 mRNA is correlated with the migration and liver metastasis of the colorectal cancer, which means FUT3 is a factor for poor prognosis of patients with colorectal cancer." (PMID 28977844, 2017). "Inhibition of FUT3 and FUT6 has been shown to affect TGF-β receptor glycosylation, resulting in decreased fucosylation as well as FUT3/6-associated sialyl Lewis antigens and altered TGF-β-mediated EMT and invasion in colorectal cancer cells." (PMID 30909444, 2019). "FUT3 overexpression promotes the fucosylation of transforming growth factor (TGF)βR-I, resulting in the activation of the TGF-β signaling pathway in colorectal cancer." (PMID 34948129, 2021). "Recently, an increase in FUT3 regulated by DDX39B catalyzes the aberrant L-fucosylation of TGFβR-I, which enhances the DDX39B-mediated TGFβ/SMAD2 signaling pathway and finally facilitates the invasion and metastasis in the colorectal cancer development." (PMID 34485140, 2021). "Though FUT6 seems to have a preference for the sialylated substrate, here, the results point towards the expression of mainly non-sialylated Lewis antigens via action of fucosylytransferases FUT3 (Lewis A) and FUT4 or FUT6 (Lewis X) in the CDX1high colorectal cancer cell lines analyzed here." (PMID 30909444, 2019).
lung adenocarcinoma (5 papers, 2022 to 2026). A carcinoma that arises from the lung and is characterized by the presence of malignant glandular epithelial cells. "CA19-9 pathway bioinformatics: CA19-9 synthesis relies on FUT3/B3GALT5; FUT3 is elevated in CA19-9-high cancers and associates with poorer prognosis in PDAC and lung adenocarcinoma." (PMID 41361823, 2025). "Nevertheless, the biological function of fucosyltransferases-3 (FUT3) in lung adenocarcinoma (LUAD) malignant phenotype remains unclear." (PMID 37946130, 2023). "Therefore, downregulation of FUT3 might inhibit the proliferation of lung adenocarcinoma cells by affecting cell cycle and proliferation-related pathways." (PMID 37946130, 2023).
lung carcinoma (5 papers, 2018 to 2023). "Emerging evidence has indicated that FUT3 enhanced migration and tumorigenesis of lung cancer, but the biological process of FUT3 in LUAD glucose metabolism was not been previously verified." (PMID 37946130, 2023). "Our study provides a theoretical basis and intervention strategy for the clinical application of FUT3 target medication in lung cancer." (PMID 37946130, 2023). "FUT3 activity was significantly elevated in the sera of patients with lung cancer compared to patients with benign diseases and healthy controls." (PMID 30619732, 2018). "Many researchers have examined the role of α-1,3-fucosyltransferase (FUT3) in the synthesis of sLex and prognosis of its physiological function in lung cancer." (PMID 30619732, 2018). "Subsequently, we analyzed the prognostic values of FUT3 in lung cancer." (PMID 37946130, 2023). "However, the correlation of FUT3 expression with glucose metabolism of lung cancer cells is unclear and remains to be elucidated." (PMID 37946130, 2023). "B3GNT3 protein expression was significantly correlated with tumor grading in lung cancer cells but not FUT3 (the only two available data from CPTAC)." (PMID 36613882, 2022).
ovarian carcinoma (5 papers, 2017 to 2024). A malignant neoplasm originating from the surface ovarian epithelium. "Elevated FUT3 expression was also observed in oral squamous cell carcinoma, breast infiltrating ductal carcinoma, and ovarian cancer." (PMID 37946130, 2023). "α3/4-Fucosyltransferases (FUT3, FUT4 and FUT9) are active in ovarian cancer development." (PMID 36231102, 2022).
gastric cancer (4 papers, 2017 to 2022). A primary or metastatic malignant neoplasm involving the stomach. "Studies have shown that human FUT3 encodes α-(1,3/4) fucosyltransferase can be associated with abnormal expression in a variety of gastric lesions, including gastritis, intestinal metaplasia, and gastric cancer, through the effect of fucosylation on intestinal diseases." (PMID 36292744, 2022). "A recent study illustrated the proliferation and other malignant properties such as migration and invasion capability of gastric carcinoma cell line can be inhibited by FUT3 gene silencing." (PMID 28977844, 2017). "According to the previous study, the down regulation of FUT3 could be a strategy to prevent high densities of H. pylori colonization in gastric cancer cell lines." (PMID 33557187, 2021). "Among the 200 primary gastric carcinomas of the referred dataset, a statistically highly significant positive association (Spearman’s rank correlation p < 0.0001) between the expression of ERBB2 and FUT3 genes was observed." (PMID 29143776, 2017).
Rotavirus infection (4 papers, 2018 to 2022). Infection with any of the rotaviruses. "Most have concluded that the presence of at least one of the genes (FUT2 and FUT3) encoding HBGA has been associated with greater susceptibility to rotavirus infection." (PMID 36560739, 2022). "A final limitation of this study was not including analysis of the related FUT3 Lewis genes as it may also impact susceptibility to rotavirus infections." (PMID 32992488, 2020). "Lewis (FUT3) and secretor (FUT2) genes appear to mediatesusceptibility to rotavirus infection.P rotaviruses only infect individuals who are Lewis-positive andsecretor-positive whereas P rotaviruses infect individuals irrespective of theirLewis and secretor status." (PMID 29466164, 2018).
ulcerative colitis (4 papers, 2016 to 2020). An inflammatory bowel disease involving the mucosal surface of the large intestine and rectum. "In particular, minor alleles of FUT3 polymorphisms appear to increase susceptibility to ulcerative colitis, whereas minor alleles of FUT2 polymorphism are associated with increased susceptibility to celiac disease, as well as increased risks of Escherichia coli and Staphylococcus aureus infections." (PMID 32133503, 2020). "Moreover, variants in both FUT2 and FUT3 have been shown in GWAS to increase susceptibility to diseases associated with both mucosal surface pathobiology and microbiome composition, such as cystic fibrosis, Crohn’s disease, and ulcerative colitis." (PMID 28143570, 2017).
oral squamous cell carcinoma (3 papers, 2017 to 2023). "High expression of FUT3 was proved to participate in the development of invasion, metastasis, and resistance to therapy by increased fucosylation activity in oral squamous cell carcinoma (OSCC), and the function could be blocked by inhibition of fucosylation." (PMID 29850522, 2018).
osteosarcoma (3 papers, 2018 to 2023). A usually aggressive malignant bone-forming mesenchymal neoplasm, predominantly affecting adolescents and young adults. "Next, survival analysis of these genes in GSE21257 which contained patients' survival prognostic information showed that osteosarcoma patients with high mRNA expression of FUT3 meant a better overall survival (OS) despite its high expression in poor chemotherapy response samples." (PMID 29850522, 2018). "Therefore, the relationship between FUT3 and tumor was so complex that little was known about its function in osteosarcoma chemoresistance." (PMID 29850522, 2018). "And many of them, such as ZNRD1, GPR68, CAT, FUT3, ANPEP, CDK1, and hsa-miR-543, might be key genes related to osteosarcoma chemoresistance." (PMID 29850522, 2018). "Among them, hsa-miR-543, as well as ZNRD1, GPR68, CAT, FUT3, ANPEP, and CDK1 genes, were proposed as crucial players in osteosarcoma chemoresistance, and hence they could represent potential therapeutic targets for osteosarcoma." (PMID 35011442, 2021).
asthenozoospermia (1 paper, 2021). "A comparison of the seminal plasma FUT3 concentration between T and AT groups suggests that asthenozoospermia may be associated with decreasing FUT3 concentration in this biological fluid." (PMID 34341430, 2021).
atopic dermatitis (1 paper, 2017). "For example, a missense variant in fucosyltransferase 3 (FUT3; rs28362459) was strongly associated with decreased abundance of Dermacoccus (the nasal vestibule in the summer), a bacteria that is depleted in the skin of individuals with atopic dermatitis." (PMID 28143570, 2017).
breast tumors (1 paper, 2016). "Previous reports have indeed suggested that expression of SLex and E-Selectin ligands was dependant on FUT3/FUT6 expression in breast tumors and cell lines." (PMID 26908442, 2016).
colitis (1 paper, 2016). Inflammation of the colon. "The frequencies of mutant allele (A) and genotype (GA+AA) of FUT3 (rs3745635) in patients with extensive colitis were significantly lower than in patients with distal colitis (P = 0.006, 95%CI: 0.553–0.845; P = 0.011, 95%CI: 0.621–0.900, respectively)." (PMID 26766790, 2016). "Furthermore, stratified analyses also indicated that the mutant alleles and genotypes of FUT3 (rs28362459 and rs3745635) were more common in patients with distal colitis than those with extensive colitis." (PMID 26766790, 2016). "Stratified analyses revealed that the frequencies of mutant allele (G) and genotype (TG+GG) of FUT3 (rs28362459) were significantly lower in patients with extensive colitis than those with distal colitis (P<0.001, 95%CI: 0.503–0.742; P = 0.001, 95%CI: 0.567–0.786, respectively)." (PMID 26766790, 2016).
distal colitis (1 paper, 2016). Particular variety of ulcerative colitis where only the left half of the colon is inflamed. "Similar conclusions were drawn for the mutant allele (A) and genotype (GA+AA) of FUT3 (rs3745635) in patients with extensive colitis compared to those with distal colitis (P = 0.006, 95%CI: 0.553–0.845; P = 0.011, 95%CI: 0.621–0.900, respectively)." (PMID 26766790, 2016). "The frequencies of mutant allele (G) and genotype (TG+GG) of FUT3 (rs28362459) were significantly lower in patients with extensive colitis than in those with distal colitis (P<0.001, 95%CI: 0.503–0.742; P = 0.001, 95%CI: 0.567–0.786, respectively)." (PMID 26766790, 2016).